WNT1 (Wnt family member 1)
Diseases named in the same sentence as WNT1 in open-access papers (continued):
Sharing a sentence is not in itself a finding about the gene and the disease.
colon cancer (16 papers, 2007 to 2025). "In particular, WISP-1 initially gained interest as a product of the oncogene Wnt1 when it was observed that its expression is increased in colon cancer cell lines and human colon tumours." (PMID 33498604, 2021). "To extend these findings we repeated the experiments with dnTCF and Wnt1 using the well-known APC mutant colon cancer cell line HT29." (PMID 26939070, 2016). "Exosomes derived from CT26 (CT26Flag-CAGE) cultures of mouse colon cancer cells stably overexpressing the tumor/testis antigen CAGE could affect autophagy flux in mouse colon cancer cells via the CAGE-miR-140-5p-Wnt1 axis." (PMID 35465266, 2022). "For instance, miR-185 may serve as a prognostic factor and inhibits migration and invasion by targeting Wnt1 in colon cancer." (PMID 31856857, 2019). "Wnt1 was present within exosomes derived from mouse colon cancer cells expressing CAGE." (PMID 31799196, 2019). "Around the same time that Elm1 was discovered, WISP1 was identified in a separate laboratory where it was found to be up-regulated by wnt1 transformed mammary epithelial cells, and in various colon cancer lines as well as being expressed in human colon cancer tissue." (PMID 23977121, 2013). "In colon cancer, ATAT1 downregulation inhibits cell proliferation and cell invasion through modulation of Wnt1/β-catenin signaling." (PMID 32498717, 2020). "Primary human colon cancer cells (CC14 and CC36) as well as metastatic colon cancer cells (mCC11) and a metastatic cell line (T84) were stably transduced with GFP+ dominant-negative TCF4 (dnTCF), Wnt1, or with control lentivectors." (PMID 26939070, 2016). "The colon cancer cell line, RKO, responded to Wnt3a CM, Wnt2 and Wnt1 by increasing canonical Wnt pathway throughput." (PMID 17386109, 2007). "We found that TREM2 inhibited the canonical Wnt1/β-catenin signaling pathway, which in turn suppressed the proliferation and tumorigenicity of HT29 colon cancer cells by inhibiting β-catenin/TCF4 transactivation activity, resulting in the suppression of cell proliferation and DNA synthesis." (PMID 31489935, 2019). "Recently, evidence at the proteomic level has suggested the involvement of the Wnt1 signaling pathway without COX activation upon indomethacin treatment in colon cancer cells." (PMID 28265497, 2017). "To test whether TMED3 KD modifies intracellular WNT localization, we chose to analyze the localization of exogenous WNT1, a WNT gene product that is expressed in colon cancer." (PMID 24920608, 2014). "Although the homolog of TMED3 in Drosophila (logjam; Strating & Martens, 2009) may not be involved in Wnt signaling, we tested for this possibility in human colon cancer cells since p24 proteins are multifunctional and TMED5 affects WNT1 secretion in 293T cells." (PMID 24920608, 2014).
hepatocellular carcinoma (16 papers, 2009 to 2025). A malignant tumor that arises from hepatocytes. "Another study demonstrated that miRNA 152 has a crucial protective role in regulating cell proliferation by inhibiting the Wnt1 signaling pathway, which is implicated in the initiation of hepatocellular carcinoma." (PMID 41465470, 2025). "Importantly, WNT-1 has been demonstrated to be significantly associated with different cancer types, including head and neck squamous cell carcinoma, thyroid carcinoma, hepatocellular carcinoma, and uterine corpus endometrial carcinoma." (PMID 37176048, 2023). "More importantly, we showed that RPPH1 supports cell viability and metastasis by activating the Wnt1/β-catenin pathway by serving as a molecular sponge for miR-122 in hepatocellular carcinoma." (PMID 36619232, 2023). "miR-148b targets the WNT1/β catenin pathway and functions as a suppressor of cell proliferation and invasion in hepatocellular carcinoma (HCC), suggesting that it may be a possible target of HCC and may prove as a treatment strategy." (PMID 32992741, 2020). "miR-122 expression level is found to be decreased significantly in human HCC tissue samples and cell lines, and overexpression of miR-122 inhibits proliferation but promotes hepatoma cell apoptosis by repressing Wnt1 expression, subsequently leads to blocking Wnt1/β-catenin/TCF signaling pathway." (PMID 29977206, 2018). "Moreover, WNT1 as a target of miR-148b has been demonstrated in hepatocellular cancer." (PMID 29415742, 2018). "Recent studies report that miR-148a is a novel microRNA that directly binds to the Wnt1 3′-UTR, to inhibit the epithelial-mesenchymal transition and cancer stem cell (CSC)-like properties of hepatocellular carcinomas (HCCs)." (PMID 28464803, 2017). "Also, Wei and coworkers studied the inhibition of Wnt-1-mediated signaling as a potential molecular target in HCC and demonstrated that Wnt-1 was highly expressed in human hepatoma cell lines and a subgroup of human HCC tissues compared to paired adjacent non-tumor tissues." (PMID 21545718, 2011).
non-small cell lung carcinoma (16 papers, 2008 to 2025). A group of at least three distinct histological types of lung cancer, including non-small cell squamous cell carcinoma, adenocarcinoma, and large cell carcinoma. "In non-small cell lung cancer, cytoplasmic WNT1 is also significantly activated and correlates with overexpression of β-catenin, c-myc and cyclin D1, and lowers 5-year survival." (PMID 37345102, 2023). "miR-148a suppressed the migration and invasion of non-small cell lung cancer cells by targeting Wnt1 signaling." (PMID 35328424, 2022). "Both Wnt-1 and Wnt-2 are up-regulated in non-small cell lung cancer (NSCLC), whereas Wnt-7a is down-regulated in most lung cancer cell lines and tumor tissues." (PMID 23815780, 2013). "Dkk3, an inhibitor of the Wnt/β-catenin pathway which is highly expressed in the normal lung has been found down-regulated in lung tumors, while the ligand Wnt1 was determined to be a prognostic factor for patients with non small cell lung cancers, NSCLC." (PMID 21753228, 2011). "Furthermore, the Wnt1 antibody also demonstrated an inhibitory effect on mesothelioma cells and the tumor growth of nude mice implanted with non-small cell lung cancer (NSCLC) cells." (PMID 32923386, 2020). "Increased expression of Wnt ligands (WNT1, 2, 7A) along with decreased expression of Wnt inhibitors (DKK3 and SFRP3) was observed in non-small cell lung cancer." (PMID 21490961, 2011). "The expression of Wnt/β-catenin pathway genes was increased in the xenograft model of primary non-small cell lung cancer (NSCLC), while Wnt/β-catenin pathway genes were significantly down-regulated after anti-HDGF treatment, especially Wnt1 and FZD were severely inhibited." (PMID 38725864, 2024).
melanoma (14 papers, 2009 to 2026). A malignant, usually aggressive tumor composed of atypical, neoplastic melanocytes. "RNAi of candidate Wnts identifies Wnt1, Wnt2, Wnt3, and Wnt7b as the specific isoforms mediating autocrine Wnt signaling in tumor cell lines M14 (melanoma), NCI-H23 (NSCLC), PA-1 (teratocarcinoma), and Hs578T (breast), respectively." (PMID 20856934, 2010). "Knockdown of endogenous oto in 293 and M14 melanoma cells dramatically increases the amount of soluble Wnt1 recovered from the media." (PMID 19593386, 2009). "We examine the effect of low oto expression on Wnt1 in vitro by knocking down endogenous oto expression in 293 and M14 melanoma cells using shRNA." (PMID 19593386, 2009). "Moreover, though the relation between Wnt1 and miR-122-5p was reported in the melanoma, the connection between IDO1 and miR-122-5p/Wnt1 in chondrogenic stimulated MSCs is reported for the first time in this study." (PMID 34956209, 2021). "The present study stimulated melanoma B16 cells with α-MSH and demonstrated the increased expression of melanin production to be accompanied with the upregulation of CSC-associated molecules (Wnt-1/β-catenin, c-Kit, MITF, and MMP-9) and invasion ability." (PMID 23762150, 2013). "Resveratrol at 15 μM could downregulate α-MSH stimulated cancer stem cell-associated molecules (Wnt-1, β-catenin and MITF expression) in melanoma B16 cells and finally decreased the cell proliferation, migration, and differentiation." (PMID 24325567, 2013). "With regards to lymphangiogenesis, however, a recent study showed that Wnt1 could protect against melanoma progression by suppressing melanoma-derived VEGF-C expression, followed by reduced lymphangiogenesis and metastasis." (PMID 23344023, 2012). "First, CRISPR activation screens in melanoma cells identify functionally diverse regulators of TCR-specific cytotoxicity, including SAFB, KHDRBS1, MYC, CD44, WNT3A, WNT1 and others." (PMID 41946842, 2026). "In preliminary studies, we have found evidence for endogenous gpi-anchored Wnt1 in untransfected M14 melanoma cells as well (JSZ unpublished), which express high levels of Wnt1." (PMID 19593386, 2009). "Mouse experiments showed that in contrast to what has been previously reported for melanoma-related b-catenin, Wnt1/b-catenin does not impact tumor cDC infiltration." (PMID 30926812, 2019). "For 293 cells, Wnt1 was cotransfected with oto shRNA (shoto), and for M14 melanoma cells, only shoto was transfected, since these cells express Wnt1 endogenously (data not shown and GNF SymAtlas)." (PMID 19593386, 2009). "Both Wnt1 and Wnt3a have been shown to activate RhoA, whereas the non-canonical Wnt5a promotes melanoma migration via RhoB." (PMID 19473496, 2009). "In NCI-H23 NSCLC cells and in M14 melanoma cells, potentiation of autocrine Wnt signaling by YW211.31 antibody and antagonism by YW210.09 are consistent with Wnt2 RNAi inhibiting endogenous signaling in NCI-H23 cells, and with endogenous Wnt1 expression in M14 cells." (PMID 20856934, 2010).
cleft palate (13 papers, 2013 to 2025). Cleft palate is a fissure type embryopathy that affects the soft and hard palate to varying degrees. "On the other hand, NC-specific expression of constitutively activated Bmpr1a (caBmpr1a, the kinase activity is ligand-independent due to the Q233D mutation) in mice (Wnt1-Cre;pMes-caBmpr1a mice) also develop cleft lip and cleft palate." (PMID 37275223, 2023). "Our findings reveal that Wnt1-Cre;pMes-Fgf18 mice exhibited cleft palate, mandibular deformation, and tongue malposition, indicating that a precise equilibrium of endogenous FGF18 signaling is essential for normal craniofacial development." (PMID 38694818, 2024). "On the other hand, neural crest (NC)-specific deletion of Bmp2 in mice (Wnt1-Cre;Bmp2fl/fl mice) develops cleft palate as a consequence of the failure of tongue descent." (PMID 37275223, 2023). "In this study, we explored the function of GAG chains in palate development through Wnt1-Cre; Fam20bf/f mice, which exhibited complete cleft palate, malformed tongue, and micrognathia." (PMID 37298583, 2023). "Thus, Wnt1-Cre and Tbx18-Cre both yielded craniofacial defects (cleft palate, macrostomia) and omphaloceles." (PMID 38079449, 2023). "Wnt1-Cre; Fam20bf/f new born die within 24 h after birth with cleft palates and micrognathia." (PMID 37298583, 2023). "We further studied the Six1f/f; Wnt1-Cre mice at E16.5 (n = 3) and E14.5 (n = 3), and found that the tongue muscle occupied the development space of the palate at E14.5, which prevented palatal lifting and led to the development of cleft palate." (PMID 36845386, 2023). "The cleft palate phenotype in Wnt1-cre;Gsαf/f mutant was tightly accompanied with dramatic craniofacial skeleton defects, therefore raising a question that whether the cleft palate resulted from a primary defect in palatal development or was secondary to craniofacial skeleton defects." (PMID 26859889, 2016). "Conditional ablation of Bmp7 with Keratin14-Cre or Wnt1-Cre revealed that neither epithelial nor neural crest-specific loss of Bmp7 alone could recapitulate the cleft palate phenotype." (PMID 23516636, 2013). "Our results demonstrated that Wnt1-Cre;pMes-Fgf18 mice exhibited the characteristic features of the PRS, such as cleft palate, abnormal tongue placement, micrognathia, and skull malformations." (PMID 38694818, 2024). "While no Cre-driver is perfectly efficient, Wnt1-Cre and Krt14-Cre have been used in multiple conditional-knockout models of cleft palate, and both ablate Ranbp1 efficiently in their appropriate compartments." (PMID 36790128, 2023). "Histological staining showed that both Wnt1-Cre; Fam20bf/f and Wnt1-Cre; pMes-caBmpr1a mice had cleft palate, while the pMes-caBmpr1a transgene (Wnt1-Cre; Fam20bf/f; pMes-caBmpr1a mice) failed to rescue the cleft palates." (PMID 37298583, 2023). "Interestingly, a new phenotype, cleft palate (70%, 7/10) with ankyloglossia, was found in Six1f/f; Wnt1-Cre mice without atrophy of tongue muscle." (PMID 36845386, 2023).
glioma (13 papers, 2014 to 2026). A benign or malignant brain and spinal cord tumor that arises from glial cells (astrocytes, oligodendrocytes, ependymal cells). "In the hundreds of previous studies, 8 members of 19 WNTs, WNT1, 2, 2B, 3A, 5A, 6, 7A and 7B, were showed being related with glioma development." (PMID 32181818, 2020). "Clinically, the protein levels of Wnt1, β-catenin and cyclin D1 were positively correlated with the Karnofsky performance scale score and World Health Organization grades of patients with glioma." (PMID 31596734, 2019). "Overexpression of WNT1 and WNT3a in glioma stem cells has been shown in the malignant transformation and progression of high-grade gliomas, WNT2 and WNT5 are also overexpressed in glioma." (PMID 28620312, 2017). "The present study indicated that targeting Wnt-1 gene expression by RNAi knockdown inhibits the growth of human glioma cells." (PMID 25435937, 2015). "In our previous study, it was demonstrated that Wnt-1 gene expression is increased in glioma, with little or weak expression identified in normal brain tissue." (PMID 25435937, 2015). "Preliminary experiments in the present study found that the Wnt-1 protein expression in human glioma was significantly higher than in normal brain tissue, and is closely associated with the degree of malignancy." (PMID 25435937, 2015). "Although a number of studies have identified a variety of tumors that exhibit abnormal Wnt-1 expression, abnormal expression is rare in glioma." (PMID 25435937, 2015). "Notably, the expression of β-catenin and Wnt-1 was significantly reduced in the combination group, followed by a significant downregulation of Nestin and β3-tubulin, markers of glioma stem-like cells and aggressiveness, respectively." (PMID 41693444, 2026). "As ligands that activate the Wnt/β-catenin signaling pathway, WNTs are widely implicated in the development of glioma, and clinical data show that expression levels of WNT5A, WNT3A and WNT1 are closely correlated with the overall survival of patients with glioma." (PMID 41184253, 2025). "WNT1 has been suggested to be overexpressed with a paradoxical role in glioma." (PMID 32181818, 2020). "A previous study showed that Wnt1 could induce expression of GLT-1 (the rodent homologue for EAAT2) in rat C6 glioma cells." (PMID 31582965, 2019). "A Wingless-type MMTV integration site family, member 1 (Wnt-1) RNA interference expression vector was constructed during the present study, which was used to transfect the glioma U251 cell line and investigate its effect on glioma." (PMID 25435937, 2015). "Therefore, the aim of the current study was to further investigate the role of Wnt-1 in glioma by RNA interference (RNAi) targeting." (PMID 25435937, 2015). "This demonstrates that glioma growth may be closely correlated with Wnt-1 protein expression." (PMID 25435937, 2015). "Furthermore, Wnt-1 expression showed a positive correlation with the glioma grade." (PMID 25435937, 2015). "These genes include HMGA1 in glioma, AKT1 in glioma, PTC, GC, and HCC, HEMGN in PTC, APLN and MMP19 in GC, WNT1 in CRC, NUPR1 in CRC and OSCC, LY6E and CTSB in CHOL, KLK4 and PLXNB2 in OC, and HDAC4 and STAT3 in SaOS." (PMID 36175921, 2022). "In glioma cell culture, additional administration of WNT5A, WNT3A and WNT1 promoted cell proliferation, which is in line with the clinical report that high expression of WNT5A, WNT3A and WNT1 correlated with short OS of patients with gliomas." (PMID 41184253, 2025). "Furthermore, WNT1 and WNT3A were found to increase glioma-derived stem-like cells chemo-resistance, proliferation and migration." (PMID 32181818, 2020). "However, the enhanced glioma proliferation induced by WNT3A, but not by WNT5A or WNT1, was diminished by CELSR2 silencing." (PMID 41184253, 2025).
Obesity (13 papers, 2012 to 2025). Accumulation of substantial excess body fat. "In obesity, miR-148a-3p is upregulated during adipocyte differentiation, promoting adipogenesis via repression of Wnt1, and its expression correlates positively with BMI in both human and mouse adipose tissues." (PMID 41009685, 2025). "The expression levels of miR-148a are increased in adipose tissues from individuals with obesity, and this effect is mediated through the suppression of its target gene, Wnt1, which serves as an endogenous inhibitor of adipogenesis." (PMID 40649784, 2025). "In the present study, we found hepatocyte-specific Wnt1 overexpression induces hepatic steatosis and obesity in HFD-fed mice." (PMID 38152126, 2023). "Conversely, pharmacological blockade of the mTOR pathway has been reported to reverse these obesity-induced effects in a model of Wnt1-induced primary mammary tumorigenesis." (PMID 30867005, 2019). "Furthermore, miR-148a promotes adipocyte differentiation by targeting Wnt1, and an elevated level of this miRNA was proposed as a biomarker of obesity in humans." (PMID 35329950, 2022). "The WNT1 gene is involved in lipid metabolism and obesity development." (PMID 30573851, 2018). "In summary, we demonstrate that hepatocyte-specific Wnt1 overexpressing mice fed by HFD develop hepatic steatosis and obesity accompanied by increased lipogenesis and disrupted β-oxidation as well as augmented Akt/mTOR signaling." (PMID 38152126, 2023). "The results suggest that miR-148a is a biomarker of obesity in humansubjects and mouse model, which represents a CREB-modulated miRNA that acts torepress Wnt1, thereby promoting adipocyte differentiation." (PMID 26001136, 2015).